INS (insulin)
Diseases named in the same sentence as INS in open-access papers (continued):
Sharing a sentence is not in itself a finding about the gene and the disease.
Insulin resistance (continued). "Previous studies have largely focused on systemic insulin resistance markers, with few studies exploring how insulin sensitivity differs across tissues in different ethnic groups using advanced quantification methods." (PMID 40987939, 2025). "Insulin resistance further exacerbates endothelial impairment by blunting insulin-mediated NO production through disrupted PI3K-Akt signaling." (PMID 41150813, 2025). "The increase in free fatty acids that consequently occurs alters the insulin signaling cascade in various organs and, thus, worsens insulin resistance in turn." (PMID 41465047, 2025). "These processes lead to β-cell dysfunction in the pancreas and thereby to impaired insulin secretion and insulin resistance." (PMID 41220583, 2025). "Hepatocellular injury frequently leads to decreased insulin sensitivity and subsequent insulin resistance." (PMID 39859525, 2025). "After adjusting for covariate (age, sex, tooth-type) effects, we found significant (p < 0.05) positive correlations between MiBP and the following CMTs: fat mass, fasting insulin, and the homeostasis model of assessment-insulin resistance (HOMA-IR)." (PMID 41154898, 2025). "Insulin resistance is defined by the impaired ability of insulin to regulate glucose metabolism in specific tissues, notably the liver, skeletal muscle, and adipose tissue, which fail to absorb glucose from the bloodstream, resulting in hyperglycemia." (PMID 40564010, 2025). "One of the primary effects of physical exercise is a reduction in insulin resistance, as exercise potentiates most of the insulin-mediated post-receptor events leading to GLUT-4 translocation to the cell surface." (PMID 39347907, 2025). "Insulin resistance is the state of impaired insulin sensitivity and glucose uptake in peripheral tissues such as muscle adipose, and liver tissue." (PMID 39815341, 2025). "Type 2 diabetes mellitus (T2DM) is a disease characterized by non-autoimmune heterogeneous progressive pancreatic islet β-cell insulin underproduction, which often occurs in the presence of insulin resistance (IR) and the metabolic syndrome (MS)." (PMID 40732347, 2025). "In WAT, G6P plays roles in insulin secretion, insulin resistance, inositol phosphate metabolism, starch and sucrose metabolism, and diabetic cardiomyopathy." (PMID 40719020, 2025). "Leptin is known to promote inflammation and insulin resistance, while adiponectin exerts protective effects on the liver by enhancing insulin sensitivity and exhibiting anti-inflammatory properties." (PMID 41347218, 2025). "Dysregulation of brain insulin sensitivity—referred to as cerebral insulin resistance—can precipitate maladaptive alterations in feeding behavior and glucose regulation, often preceding the onset of overt hyperglycemia." (PMID 40869170, 2025). "Insulin resistance affects brain insulin signaling and perfusion and cortical activities in brain regions with high energy demands, such as cognitive-related networks." (PMID 40392946, 2025). "The homeostatic model assessment for insulin resistance will be used to assess insulin sensitivity, while 16S rRNA V3-V4 region sequencing will be conducted to profile gut microbiota composition." (PMID 41370820, 2025). "Insulin resistance leads to elevated levels of insulin and insulin-like growth factors, which can promote the growth of cancer cells." (PMID 40510154, 2025). "Such oxidative stress can impair pancreatic islet cell function and reduce insulin secretion and activity, leading to insulin resistance (IR)." (PMID 39897593, 2025). "This is followed by the development of insulin resistance, characterized by a reduced cellular response to insulin and consequently impaired glucose uptake." (PMID 40565645, 2025). "Endogenous basal insulin is a major component of the daily insulin profile, serving as a key indicator of insulin resistance and a predictor of impaired glucose tolerance and T2DM." (PMID 40428172, 2025).
Insulin resistance (continued). "In T2D, early stages are characterized by increased insulin secretion to compensate for insulin resistance; however, over time, β cells fail to sustain this elevated output, leading to relative insulin deficiency." (PMID 40919135, 2025). "This is crucial because adipose tissue inflammation can disrupt insulin signaling, contributing to insulin resistance." (PMID 40641901, 2025). "Higher BMI was significantly correlated with increased 2 h insulin levels, reinforcing the role of obesity in exacerbating insulin resistance." (PMID 40868057, 2025). "Lactic acid produced by Collinsella can lead to insulin resistance by inhibiting muscle glycolysis and interfering with insulin signaling." (PMID 40230807, 2025). "Males also have a higher insulin resistance in both photoperiods, which results in increased compensatory insulin secretion and thus higher leptin production." (PMID 40493338, 2025). "Mendoza and Parsiani reported the case of a 23-year-old woman with T1D since the age of 10 years who was referred to the outpatient clinic due to insulin resistance and increasing insulin requirements." (PMID 40004833, 2025). "Excessive adipose tissue accumulation in sheep disrupts insulin signaling, inducing insulin resistance, and alters energy partitioning mechanisms." (PMID 41153973, 2025). "These antioxidants alleviate stress on pancreatic beta cells and tissues, improving insulin sensitivity and secretion, critical for combating insulin resistance and supporting weight management." (PMID 39861488, 2025). "Together, these led to altered insulin action in the liver and identified important targets for the therapy of hepatic insulin resistance." (PMID 40231468, 2025). "Human insulin can activate IRS-1 phosphorylation on Ser-307 and mice fed on a high-fat diet; an IRS-1 Ser307Ala mutant exhibited more severe insulin resistance than controls, demonstrating that Ser-307 is essential for insulin signaling." (PMID 40141412, 2025). "A gradual increase in insulin resistance requires a markedly increased amount of insulin to overcome hyperglycemia, resulting in a complex interaction between insulin secretion and insulin resistance in the liver and skeletal muscle." (PMID 41012462, 2025). "Data from an experimental study using miR-375 KO and miR-375/obese KO mice revealed hyperglycemia due to an increase in pancreatic α-cell mass, impaired glucose tolerance, and reduced insulin secretion—hallmarks of insulin resistance in the miR-375 KO group." (PMID 40408591, 2025). "Congruently, we found that eGFR levels correlated inversely with insulin sensitivity, with higher eGFR denoting greater insulin resistance, a key feature of metabolic syndrome." (PMID 41163811, 2025). "Type 2 diabetes mellitus (T2DM) is a complex chronic metabolic disease characterized by insulin resistance and insufficient insulin secretion." (PMID 40883486, 2025). "Insulin resistance, a pathophysiological condition, diminishes cellular responsiveness to insulin, thereby initiating hyperglycemia." (PMID 41023603, 2025). "This suggests that the high carbohydrate content (>60%) of the SD likely contributed to increased triglycerides and insulin resistance, consistent with the literature indicating that high-carbohydrate diets increase fasting insulin and resistance." (PMID 40622971, 2025). "Type 2 Diabetes (T2D) is the most common form of the disease, primarily affecting adults and resulting from insulin resistance or inadequate insulin production." (PMID 40430489, 2025). "We analyzed the relationships between various clinical parameters, including adrenal hormones, and insulin secretion (homeostatic model assessment [HOMA2-%B]) or insulin resistance (HOMA2-IR)." (PMID 40296149, 2025). "In adults with MetS and impaired glucose regulation, both insulin-based and non-insulin-based indices of insulin resistance increased with worsening metabolic profile." (PMID 41465784, 2025).
Insulin resistance (continued). "In humans, insulin resistance/sensitivity is in part regulated by the circadian system, and exhibits a clear diurnal pattern, with higher insulin sensitivity in the morning and lower sensitivity later in the day and at night." (PMID 39982484, 2025). "Among the 13 lipids positively linked with physical activity levels, 6 showed positive associations with insulin sensitivity (QUICKI), while weak correlations with fasting glucose and insulin resistance were observed." (PMID 41286497, 2025). "Reduced APN levels correlate with heightened insulin resistance, elevated blood glucose, and impaired insulin sensitivity." (PMID 40332110, 2025). "Type 2 diabetes (T2D) is preceded and modified by insulin resistance (IR), a condition in which cells fail to respond effectively to insulin, disrupting glucose and lipid homeostasis." (PMID 40659091, 2025). "In a human lipidomic study, specific PI species, including PI (32:1) and PI (40:6), were found to be positively correlated with insulin levels and HOMA-IR, indicating a potential association between specific PI species and insulin resistance." (PMID 41002958, 2025). "The ratio between leg fat and total fat measured by DEXA was higher in youth with insulin sensitivity (0.19 ± 0.016) than in those showing insulin resistance (0.17 ± 0.019) (P = 0.001)." (PMID 40091831, 2025). "Other examples of therapeutic interventions targeting insulin resistance are the insulin-sensitizing hormone glucagon-like peptide 1 (GLP1) and metformin." (PMID 40137124, 2025). "Studies have demonstrated that Ang II inhibits insulin-mediated PI3K pathway activation, thereby impairing endothelial NO production and Glut-4 translocation in insulin-sensitive tissues, which results in vascular and systemic insulin resistance, respectively." (PMID 40564980, 2025). "In the context of insulin resistance, elevated serum insulin levels increase ovarian androgen production and inhibit hepatic sex-hormone binding globulin (SHBG) production, thereby synergistically boosting free testosterone levels." (PMID 40529393, 2025). "Insulin resistance reduces the anti-inflammatory effect of insulin, leading to chronic inflammation." (PMID 40375945, 2025). "The estimated glucose disposal rate (eGDR), originally developed to assess insulin sensitivity in type 1 diabetes, has emerged as a valuable surrogate marker for insulin resistance." (PMID 40256390, 2025). "Visceral fat releases cytokines such as TNF-α and IL-6, which impair insulin action and exacerbate insulin resistance, even in individuals with a normal body mass index (BMI)." (PMID 41002975, 2025). "High Se intake and elevated levels of selenoproteins can impair insulin signaling, leading to hyperglycemia and insulin resistance." (PMID 39942544, 2025). "Chronic inflammation driven by TLR activation alters insulin signaling, leading to insulin resistance." (PMID 40076851, 2025). "Recognized as a type of diabetes and referred to as “Type 3 diabetes” (T3D), AD occurs through impaired insulin signaling in the hippocampus and the concurrent development of insulin resistance." (PMID 40869265, 2025). "In an attempt to compensate for this metabolic dysfunction, the pancreas secretes more insulin; however, as the insulin resistance progresses, the pancreatic β-cells are damaged and contribute to the pathogenesis of T2DM." (PMID 41220583, 2025). "Individuals with moderate-to-severe OSA exhibit peripheral insulin resistance in the skeletal muscle and adipose tissue, even though hepatic insulin sensitivity remains unaffected." (PMID 40565914, 2025). "RBP4 is increased with insulin resistance; it increases adipocyte basal lipolysis and reduces the ability of insulin to suppress lipolysis (which also leads to ectopic liver fat accumulation) and has been implicated in immune stimulation." (PMID 41416660, 2025).
Insulin resistance (continued). "Prevents insulin resistance, reduces fasting glucose and insulin levels, improves glucose tolerance, enhances energy metabolism, reduces lipid peroxidation, and increases mitochondrial content." (PMID 39963239, 2025). "Along with the increased secretion of proinflammatory cytokines (TNF-α and IL-6), adipose tissue macrophage infiltration and activation contribute to insulin resistance and impaired insulin signalling." (PMID 40216734, 2025). "This activation leads to increased production of pro-inflammatory cytokines, which disrupt insulin signaling and promote insulin resistance." (PMID 40136728, 2025). "Studies have shown that supplementation with 50,000 IU of vitamin D every 2 weeks improves insulin resistance and reduces fasting insulin and total cholesterol levels." (PMID 39963668, 2025). "High-quality muscle tissue enhances insulin signaling and reduces insulin resistance, thereby improving metabolic syndrome profiles and reducing cardiovascular risk." (PMID 41299285, 2025). "This is because TZDs reduce insulin resistance, thereby lowering the secretory burden on β cells, whereas secretagogues stimulate insulin release." (PMID 41155022, 2025). "The accumulation of IMCLs interferes with insulin signaling, contributing to insulin resistance in muscle tissue." (PMID 40807122, 2025). "Our results indicated that leptin decreased with the morning HC dose, and we suspect that the development of steroid-induced insulin resistance also involves an impaired signalling dialogue between leptin and insulin." (PMID 40795401, 2025). "The month earlier, she had started extended-release metformin (titrated to 1000 mg/day) to reduce insulin resistance and insulin requirements and improve glucose control." (PMID 40004833, 2025). "Dysglycemia is also a frequent yet underrecognized complication, arising from catecholamine excess which impairs glucose homeostasis via suppressed insulin secretion, induced insulin resistance, and increased hepatic glucose production." (PMID 41585808, 2025). "This splicing alteration directly impairs skeletal muscle sensitivity to insulin, serving as an important molecular basis for insulin resistance in DM1 patients." (PMID 41018201, 2025). "The overlapping mechanisms between PCOS, suicidality, and insulin resistance underscore the importance of considering insulin modulation as a potential therapeutic target." (PMID 40457354, 2025). "The pathophysiology of T2DM involves both insulin resistance and a progressive decline in insulin secretion, ultimately leading to chronic hyperglycemia." (PMID 41157216, 2025). "Among adipocytokines, leptin is associated with insulin resistance via shared signaling pathways—such as JAK2/STAT3, MAPK, and PI3K—with insulin in the placenta." (PMID 40725173, 2025). "In type 2 diabetes, insulin resistance—where target tissues, including skeletal muscle, adipose tissue, and liver, become less responsive to insulin—plays a central role in disrupting glucose homeostasis." (PMID 39942757, 2025). "Insulin resistance-driven glucolipotoxicity harms β-cells through mechanisms like endoplasmic reticulum (ER) stress and disrupted insulin signaling." (PMID 40363798, 2025). "T2D arises when pancreatic β-cells fail to compensate for increased insulin resistance, with cytokines playing a significant role in both insulin and leptin resistance, contributing to β-cell dysfunction." (PMID 40362828, 2025). "Endothelial dysfunction can affect the transport and action of insulin, preventing it from reaching its target tissues effectively, thereby exacerbating insulin resistance." (PMID 41211213, 2025). "In IFG, impaired initial insulin response to oral glucose normalizes in the later phase (60 to 120min), combined with severe hepatic insulin resistance, lead to abnormal FPG." (PMID 40375950, 2025). "Third, insulin resistance during sepsis blunts the lipogenic activity of insulin and promotes lipolysis." (PMID 39838305, 2025).
Insulin resistance (continued). "Brain insulin resistance is an important pathogenetic feature of AD and is mediated primarily by impaired insulin signaling (Sêdzikowska and Szablewski, 2021)." (PMID 40778306, 2025). "In most women, the body’s compensatory mechanisms, primarily the beta-cell expansion and increased insulin secretion, are sufficient to overcome this insulin resistance and maintain glucose homeostasis." (PMID 40076938, 2025). "Second, due to GWAS limitations, the authors used fasting insulin levels as a proxy for insulin resistance." (PMID 40669383, 2025). "Collectively, reduced response within the canonical insulin signaling pathway, reduced mitochondrial function, and heightened reactive oxygen species (ROS) are all common features of palmitate-mediated insulin resistance in C2C12 myotubes." (PMID 41305671, 2025). "We further explored the hepatic protein expression of the insulin signaling pathway to confirm the involvement of insulin resistance in fatty liver." (PMID 40141836, 2025). "In T2D, the abnormal activation of immune cells can interfere with the insulin signaling pathway, reducing insulin sensitivity and exacerbating insulin resistance." (PMID 40469434, 2025). "Insulin resistance itself is otherwise known as impaired cellular sensitivity to insulin, the hormone responsible for allowing glucose from the blood into cells." (PMID 40901288, 2025). "Also, there are notable differences in adipose tissue distribution and insulin sensitivity between the sexes with women tending to have greater subcutaneous fat deposition, while men accumulate more visceral adiposity—a known risk factor for insulin resistance and prediabetes." (PMID 40600010, 2025). "Impaired ability of insulin to suppress endogenous glucose synthesis, 45–50% reductions in glucose disposal and a measure of whole-body insulin sensitivity are the indicative of hepatic insulin resistance." (PMID 40893881, 2025). "Many studies in pregnancy have used mathematical indices, such as HOMA scores, Matsuda and Stumvoll indices, which use glucose and insulin concentrations to assess insulin resistance or secretion." (PMID 39621104, 2025). "Ghrelin engages incretin and insulin signaling cascades, perturbations of which foster insulin resistance in the obese state and thereby presage the onset of T2DM." (PMID 41190158, 2025). "In the context of insulin resistance, various defects compromise the normal functioning of the insulin signaling pathway, leading to impaired glucose uptake and metabolism." (PMID 39940428, 2025). "Various factors contribute to the so-called multifactorial insulin resistance, including genetic, molecular, physiological, and metabolic pathways that result in diminished insulin action in peripheral tissues, such as muscle and adipose tissues." (PMID 40141412, 2025). "Conversely, adiponectin, which enhances insulin sensitivity and fatty acid oxidation, is significantly reduced in obesity, contributing to insulin resistance and metabolic dysfunction." (PMID 40429763, 2025). "Participants with advanced insulin resistance had significantly higher levels of P2 platelets (p=0.03) and significantly lower levels of P3 (p=0.006) when compared with those with normal insulin sensitivity." (PMID 40304758, 2025). "As insulin resistance progresses, glucose uptake in muscle tissue further decreases, leading to elevated postprandial plasma glucose levels and excessive insulin secretion." (PMID 40951687, 2025). "In general, obese adipose tissue has a high number of M1 macrophages with insulin resistance, while healthy adipose tissue has a high number of M2 macrophages with higher insulin sensitivity." (PMID 40781882, 2025). "In the case of insulin resistance, its receptors on the cell membrane fail to bind with insulin and trigger its signaling cascade, facilitating, eventually, glucose uptake via glucose transporter type 4 (GLUT4)." (PMID 41473651, 2025).